IL1RL1 (interleukin 1 receptor like 1)
Diseases named in the same sentence as IL1RL1 in open-access papers (continued):
Sharing a sentence is not in itself a finding about the gene and the disease.
asthma (continued). "SNP rs1420101 (located in IL1RL1) is a variant affecting the quantity of eosinophil in pleiotropic multifunctional leukocytes, which is involved in inflammatory and immune responses observed in asthma, eczema, rhinitis, and other inflammatory diseases." (PMID 29378629, 2018). "These include the genes IL33 and IL1RL1, and sequence variants in the human genome close to these genes were initially found to affect the number of eosinophils, cells that play a role in inflammation of the airways in asthma." (PMID 28273074, 2017). "Recently the genes encoding IL-33 and ST2 (also known as interleukin-1 receptor-like 1, IL-1RL1), have been identified as important factors for human asthma in several genome-wide association studies that included thousands of patients from diverse ethnic groups having different forms of asthma." (PMID 27310495, 2016). "A functional SNP in IL1RL1 is associated with asthma in human." (PMID 26083354, 2015). "The potential involvement of IL-33 in the etiology of asthma has attracted considerable attention as a consequence of recent large-scale genome-wide association and polymorphism studies that link the genes for IL-33 (IL33) and its receptor (IL1RL1) to asthma susceptibility." (PMID 26214807, 2015). "Moreover, genetic dysregulation of the IL-33/IL1RL1 axis appears to be involved in conferring predisposition to several multifactorial diseases, such as Alzheimer’s disease, asthma, nasal polyposis, allergic rhinitis, and atopic dermatitis." (PMID 23634226, 2013). "A recent large scale genome-wide association study of asthma found associations between asthma and SNP rs3771166 on chromosome 2 implicating a role for IL1RL1, but also variants at different loci associated with different types of asthma, such as childhood asthma." (PMID 22574108, 2012). "IL1RL1 gene cluster polymorphisms were found to be associated with asthma and atopy." (PMID 22574108, 2012). "Moreover, polymorphisms in the IL1RL1 gene are associated with the onset of asthma in Caucasian populations." (PMID 22808055, 2012). "An IL1RL1 single nucleotide polymorphism (SNP) was among the most significant results of a genome-wide scan investigating eosinophil counts; in the same study, this SNP associated with asthma in 10 populations." (PMID 21629437, 2010). "Polymorphisms in IL18R1, a gene in tight LD with IL1RL1, were associated with asthma, atopic asthma and airway hyper-responsiveness using a candidate gene approach in a Danish population and the association consistently replicated in two other European populations." (PMID 21629437, 2010). "Three intronic SNPs in the IL1RL1 gene were also associated with asthma." (PMID 19852851, 2009). "Many SNPs in the IL1RL1 gene were associated with asthma in the SLSJ study." (PMID 19852851, 2009). "We hypothesised that different isoforms of IL33, that may be more prevalent in the airways of patients with asthma, may differentially activate IL1RL1 and that asthma‐associated IL1RL1 nonsynonymous variation may further modify the magnitude of this signalling response." (PMID 39301832, 2024). "We suggest that this novel finding may be particularly important in asthma patients that carry IL1RL1 asthma risk alleles and have a lung microenvironment that promotes elevated levels of cleaved IL33 isoforms, leading to a more IL33‐driven disease amenable to targeting." (PMID 39301832, 2024). "The interleukin 1 receptor-like 1 gene (IL1RL1) has been considered in numerous genome-wide association studies (GWASs) as a gene for asthma susceptibility, response to inhaled corticosteroids (ICS), and the significant increase in serum IgE, and could affect the response to omalizumab." (PMID 37108192, 2023). "IL1-RL1 may be used as a potential diagnostic markers and therapeutic targets in asthma." (PMID 35578178, 2022).
asthma (continued). "Other robust asthma associations have been found in and near IL33, TSLP, and IL1RL1, supporting the notion that epithelial cell-derived cytokines play a critical role in promoting the differentiation and activation of T helper 2 (Th2) cells in asthma pathogenesis." (PMID 28774304, 2017). "The IL-33/IL1RL1 pathway plays a crucial role in host defense and in the pathogenesis of immune-mediated, allergic, and chronic inflammatory diseases such as asthma, dermatitis, arthritis, and Alzheimer’s disease." (PMID 39595128, 2024). "For example, IL1RL1/IL18R1, IL33 and TSLP have emerged as important genes associated with the development of asthma." (PMID 39694589, 2024). "IL-33-ST2, also known as the IL-1RL1 axis, is considered the chief culprit in allergic diseases such as asthma, atopic dermatitis, and autoimmune disorders." (PMID 39719880, 2024). "The IL33/IL1RL1 axis represents a therapeutic opportunity for asthma and allergic diseases and is of interest for several pharmaceutical companies developing selective inhibitors/blocking antibodies." (PMID 39301832, 2024). "Our results show that maximal IL1RL1 signalling requires the presence of both TIR signalling domain and rs1041973 asthma risk variants, which is a novel finding." (PMID 39301832, 2024). "Genome-wide association studies have also identified several key epithelial-expressed genes and gene networks associated with an increased asthma risk, including TSLP, IL33 and IL1RL1 (an IL-33 receptor)." (PMID 38453256, 2024). "HEK293 cells carrying both asthma extracellular and TIR domain IL1RL1 risk haplotypes presented maximal IL33‐driven signalling, with minimal signalling after IL‐33 activation in other protective haplotypes." (PMID 39301832, 2024). "The mRNA expression for IL1RAP, the IL1RL1 co‐receptor, was greatest in severe neutrophilic and mixed granulocytic asthma." (PMID 35986608, 2023). "Genome-wide association studies have indicated that IL-33 and IL1RL1 (encoding ST2), which have obvious links to ILC2 biology, are associated with asthma susceptibility." (PMID 35911708, 2022). "Recently, a phase II clinical trial with anti-IL-1RL1 (astegolimab) showed that this drug significantly reduced asthma exacerbations in a broad population of patients, with inadequately controlled, severe asthma." (PMID 35197433, 2022). "Another proinflammatory candidate, cytokine Il33, and its receptor Il1rl1 are both upregulated in Mmp3hi HAFs and are characteristic of fibrotic lung diseases, such as asthma." (PMID 35439171, 2022). "Genome-wide association studies in patients with asthma showed that IL33 and IL1RL1 (ST2) were the genes most associated with asthma." (PMID 35025767, 2022). "The GWAS study reported in 2018 included some loci of the IL1RL1 gene region in the list of asthma highly related SNPs in Europeans." (PMID 34977013, 2021). "Some genes such as TSLP, IL-33 and its receptor IL1RL1 have well-established asthma inflammatory roles." (PMID 35386986, 2021). "TWAS genes of known biological interest in asthma include IL1RL1 on 2q12, TLR1 on 4p14, TSLP on 5q22, SMAD3 on 15q22-q23, and IL4R on 16p12." (PMID 34103634, 2021). "The GRSs for WHR (N = 11), estimated glomerular filtration rate (eGFR; N = 7), and CAD (N = 4) were associated with higher as well as lower abundance of different aptamers, and the asthma-GRS was specifically and positively associated with IL1RL1." (PMID 33328453, 2020). "In summary, we identify that IL1RL1 genetic signals potentially contribute to severe and eosinophilic phenotypes in asthma, as well as provide initial mechanistic insight, including genetic regulation of IL1RL1 isoform expression and receptor signaling." (PMID 32324168, 2020). "They concluded that certain SNP occurrences in genes such as CD247, ERBB2, IL1RL1 and several interleukin family genes are strongly correlated with moderate-to-severe asthma." (PMID 32512817, 2020).
asthma (continued). "Carriers of the asthma protective allele in Signal A (rs995514; CC) and Signal D (rs10192157; TC/TT) responded to HDM through elevations in soluble IL1RL1 protein." (PMID 32324168, 2020). "Bronchial epithelial cell cultures from asthma patients, exposed to exacerbation-relevant stimulations, revealed modulatory effects for all 4 signals on IL1RL1 mRNA and/or protein expression, suggesting SNP-environment interactions." (PMID 32324168, 2020). "Prior links between these proteins and asthma or atopy exist (IL1RL1 and IL1RL2, IL2RA, IL4R, and IL6R), albeit not necessarily strong evidence for a causal link." (PMID 32628676, 2020). "These include GWAS studies revealing several genes essential in ILC2 biology as susceptibility markers for human asthma such as the ILC2-activating alarmin IL-33 and its cognate receptor ST2 (IL1RL1) as well as the transcription factors GATA3 and RORα." (PMID 31231357, 2019). "More importantly, 11 mRNAs were overlapped in our sequencing data, MalaCards database and asthma-associated genes, including IL4, IL-10, MMP9, VCAM-1, Il1rl1, Alox5, Il1rn, Ccr3, Cysltr1, Epx, and Ccl24." (PMID 31231429, 2019). "Asthma is associated with variants in the genes encoding IL-33 and its receptor ST2 (also known as ST2L and IL1RL1)." (PMID 30174671, 2018). "Genes such as HLA, IL13, IL33, thymic stromal lymphopoietin (TSLP) involved in Th2 pathway, IL-1 receptor–like 1 (IL1RL1), encodes ST2, and the receptor for IL-33 are associated with asthma onset." (PMID 29904594, 2018). "As a major finding of these projects, asthma onset has been associated with a number of genes coding for HLA, IL-13, IL-33, thymic stromal lymphopoietin [TSLP], IL-1 receptor-like 1 [IL-1RL1], ST2, and the receptor for IL-33." (PMID 29992143, 2018). "A number of prior GWAS have identified distinct genetic susceptibility for pediatric onset asthma, particularly implicating ORLDM3/GSDMB, IL1RL1, and IL13, which were all found to have association with childhood asthma in the current analysis." (PMID 30373671, 2018). "Through GWAS, we previously discovered common sequence variants in IL1RL1 and IL33 that associate strongly with blood eosinophil counts and risk of asthma, consistent with the link between eosinophilic inflammation and asthma." (PMID 28273074, 2017). "Further support of this role comes from murine models and large-scale genome-wide association studies in which asthma-susceptibility loci have been identified in the regions for IL33 and the cognate receptor for IL-33, IL1RL1 (i.e. ST2)." (PMID 26318341, 2015). "The IL-33/IL1RL1 pathway plays an important role in host defense and in autoimmune, allergic, and chronic inflammatory disorders, such as asthma, dermatitis, rhinitis, arthritis, diabetes mellitus, atherosclerosis, and Alzheimer’s disease." (PMID 23634226, 2013). "A study in an Icelandic cohort showed significant association with asthma and a SNP in IL1RL1 and SNPs in PDE4D have also shown association with genome-wide significance with asthma." (PMID 24066901, 2013). "A GWA study of eosinophil counts with follow-up testing in asthma case-control studies identified variants near IL1RL1/IL18R1 and IL33 as being associated with asthma." (PMID 23028483, 2012). "They observed associations with asthma, particularly childhood-onset asthma, at multiple loci (ORMDL3/GSDMB, IL1RL1/IL18R1, HLA-DQ, IL33, SMAD3, and IL2RB)." (PMID 23028483, 2012). "This is consistent with previous studies showing that higher IL1RL1-a serum concentrations were correlated with other clinically severe diseases such as acute heart disease and asthma." (PMID 22574108, 2012). "Clearly IL1RL1's subnetwork is enriched for canonical asthma genes (P = 1.8×10−07) making it the most likely gene driving the asthma association on 2q12." (PMID 23209423, 2012). "Clinical and genetic studies indicate that IL1RL1 plays an important role in the development and exacerbations of asthma." (PMID 22574108, 2012).
asthma (continued). "We also describe the role of IL1RL1 in asthma, allergy, cardiovascular disease, infections, liver disease and kidney disease." (PMID 21629437, 2010). "In the same year, another candidate gene association study documented significant genetic association of the gene cluster containing IL1RL1, IL18R1 and IL18RAP with asthma and atopy in a Dutch population." (PMID 21629437, 2010). "A number of SNPs in the IL10, CYP24A1, CYP2R1, IL1RL1 and CD86 genes were modestly associated with asthma and atopy (p < 0.05)." (PMID 19852851, 2009). "SNPs located in five genes, including IL10, CYP24A1, IL1RL1, CYP2R1 and CD86, showed modest association with asthma or atopy in an asthma family study derived from the Saguenay_Lac-Saint-Jean population." (PMID 19852851, 2009). "A recent study revealed increased expression of IL1RL1/ST2 on neutrophils in a preclinical model of asthma following rhinovirus infection and increased production of NETs and type 1 and 2 cytokines by isolated blood neutrophils in these conditions following IL-33 stimulation." (PMID 41124071, 2025). "Analyzing additional SNPs in STAT6 (e.g., rs324015, rs3024944, rs71802646) and other genes (e.g., IL1RL1, GATA3, ADAM33, TSLP, FOXO3a) would expand the scope of genetic analysis and provide a comprehensive understanding of asthma susceptibility in the population." (PMID 40375219, 2025). "As another example, IL1RL1 pQTLs colocalised with IL1RL1, IL18R1 and IL18RAP eQTLs detected in multiple cell types with direct effects on the immune system (e.g. T-cells); these variants were associated with asthma and allergic reactions in the PheWAS." (PMID 38565889, 2024). "This highlights the potential of the IL-33/IL1RL1 axis in modulating IBD susceptibility and the shared inflammatory pathways between IBD and respiratory diseases like asthma, suggesting personalized treatment options for IBD patients resistant to certain therapies." (PMID 39144148, 2024). "These new findings may facilitate the identification of patients more (or less) amenable to IL33/IL1RL1 blocking strategies targeting this pathway for clinical benefit in asthma." (PMID 39301832, 2024). "These cell‐based data suggest that the airway microenvironment, which drives the formation of different IL33 isoforms, in combination with IL1RL1 nonsynonymous genetic variation, may determine the inflammatory response in specific asthma patients." (PMID 39301832, 2024). "Additionally, uPAR overexpression universally caused changes in the expression of genes related to cellular proliferation (BRICD5) and T‐cell/B‐cell signaling (LCK/LIME1) and importantly asthma via the IL33 receptor (IL1RL1), now a target for new asthma drugs." (PMID 37876037, 2023). "The ST2 is a product of the IL1RL1 gene, a known asthma locus." (PMID 36434743, 2022). "Similarly, genetic variations of the interleukin-1 receptor-like 1 (IL1RL1) gene have also been related with asthma exacerbations in children." (PMID 36226150, 2022). "However, it was observed that children with asthma who had the TT genotype of rs1420101 or AA genotype ofrs4142132 in the first intron of IL1RL1, responded better to ICS treatment in PBEC." (PMID 34977013, 2021). "This strongly suggests that a single signal may drive the differential expression of multiple genes and contribute to asthma mechanisms in multiple ways, the IL1RL1 signal remains one of the most reproducible asthma signals potentially for this reason." (PMID 35386986, 2021). "Following detection of known common variation in the locus, we identified coding and noncoding variation through resequencing of the IL1RL1 locus in 2 European populations of asthma patients in order to provide improved understanding of the genetic variation in the IL1RL1 region." (PMID 32324168, 2020).
asthma (continued). "This has implications for the targeting of the IL-33/IL1RL1 axis inhibitors to a subset of patients of a specific genotype likely to gain the greatest clinical benefit and is highly relevant, with multiple pharmaceutical companies developing anti–IL-33/IL1RL1 approaches for the treatment of asthma." (PMID 32324168, 2020). "IL1RL1 variation has an impact on IL1RL1 regulation in response to asthma-relevant stimuli." (PMID 32324168, 2020). "Because asthma is known to be a multifactorial and heterogeneous disease, we hypothesize that different SNPs within the IL1RL1 locus drive different subtypes or components of asthma via independent and overlapping functional effects." (PMID 32324168, 2020). "Exon resequencing of the IL1RL1 gene in an additional 95 asthma patients (Dutch Asthma GWAS [DAG]), carried out to increase our pool of sequenced asthma patients, identified a total of 56 variants covering the gene’s distal and proximal promoter, introns, and exons." (PMID 32324168, 2020). "The G allele of the polymorphism of the IL33 gene, rs12551256, showed a negative correlation with asthma, whereas the A IL1RL1 gene allele, rs1041973, correlated with the production of IL-5 in the serum, sIgE levels, and positive scores of skin prick tests." (PMID 30304837, 2018). "Since eosinophils are known to play a key role in inflammation of the airway in asthma we used high-coverage sequencing to search for novel sequence variants affecting eosinophil counts at the well established asthma loci, the IL33 and IL1RL1 loci, and tested their effects on asthma." (PMID 28273074, 2017). "The association between IL1RL1 and IL33 variants and asthma risk is well established and has been replicated in ethnically diverse populations, and in severe forms of adult asthma and in particular with early childhood asthma with exacerbations." (PMID 28273074, 2017). "In addition, genes discovered in genome-wide association studies of asthma (RORα, IL-13, IL-33, IL-1RL1; which are all related to ILC2) suggest a key role for ILC2 in asthma." (PMID 26727464, 2016). "There is increasing evidence that IL1RL1 plays an important role in the development of asthma." (PMID 22574108, 2012). "IL1RL1 SNPs were associated with allergy and asthma phenotypes as single SNPs although the significance did not survive multiple testing correction." (PMID 21629437, 2010). "Using asthma mouse models, it was shown that eosinophilic inflammation is significantly decreased following allergic stimuli in animals subjected to treatments with recombinant IL1RL1 or antibodies directed against the membrane-anchored protein." (PMID 21629437, 2010). "No other SNP in the IL1RL1 gene was associated with asthma or atopy in the replication studies except a non-synonymous coding SNP (rs1041973, Glu78Ala) that was borderline significant for atopy in SAGE." (PMID 19852851, 2009). "This issue could also explain the lack of any significant associations between IL1RL1 gene variants and asthma in a study of a Puerto Rican population." (PMID 36292755, 2022). "Interestingly, Signal A — associated with asthma and blood eosinophils — did not demonstrate any IL1RL1 eQTL association in lung tissue." (PMID 32324168, 2020). "IL1RL1 coding region variants associated with asthma do not modify TLR signaling." (PMID 32324168, 2020). "Thus, our data suggest cell type specificity of eQTL for IL1RL1, suggesting that specific subtypes of asthma may be driven by different cell types in different patients." (PMID 32324168, 2020). "One example of the SNP of IL1RL1 that predisposes to both atopic and non-atopic asthma and is connected with eosinophilia, causing an increased level of serum IgE and airway hyperresponsiveness, is rs950880 for non-Islandic population (in Islandic population it is rs1420101)." (PMID 31057533, 2019).